ALB (albumin)
Diseases named in the same sentence as ALB in open-access papers (continued):
Sharing a sentence is not in itself a finding about the gene and the disease.
liver disease (continued). "We were unable to provide Child-Pugh classification for patients with advanced liver disease due to lack of serum albumin evaluation in a significant number of patients, as at that time, it was not a routine test in our clinic." (PMID 33652777, 2021). "Participants with albumin <30g/l, liver disease, <18 years, of non-Black or non-White self-reported ethnicity were excluded." (PMID 34383841, 2021). "More recently, the positive impact of long-term albumin supplementation in liver disease, based on its pleiotropic non-oncotic activities, has been recognized." (PMID 34836265, 2021). "The etiology of liver diseases comprised non-hepatitis B or C virus in 35.3% (40/113) of patients, the median albumin-bilirubin (ALBI) score was −2.4, and ALBI grade 1 was observed in 38.9% (44/113) of patients." (PMID 33466496, 2021). "Association between ALB, ALT, AST, and total bilirubin with prognosis of cardiac surgery patients without liver disease." (PMID 34790710, 2021). "The following patient’s clinical characteristics were registered: age, gender, etiology of liver disease, liver function parameters (INR, total bilirubin level, serum creatinine, serum albumin), MELD score, Child Pugh class, the presence of ascites, and baseline AFP level (ng/mL)." (PMID 32793278, 2020). "The findings also suggest that zinc is unlikely to contribute to decreased albumin concentrations in patients without liver diseases." (PMID 31392541, 2020). "Our own preliminary data on nonviral liver disease indicates the presence of autoantibodies against albumin in patients with liver cirrhosis (unpublished data)." (PMID 30930689, 2019). "Albumin levels are frequently tested in patients with liver disease, and albumin is part of the widely used Child–Pugh–Turcotte (CPT) score to determine the stage of liver disease." (PMID 31717529, 2019). "The utilization of albumin to manage the complications of cirrhotic disease includes management of ascites with large volume paracentesis (LVP), spontaneous bacterial peritonitis (SBP), and hepatorenal syndrome (HRS)." (PMID 31278624, 2019). "Usually, the values of ALT, AST, ALB, and ALP would increase accompanying the liver disease." (PMID 29692735, 2018). "Recommendation 1: Initial investigation for potential liver disease should include bilirubin, albumin, ALT, ALP and GGT, together with a full blood count if not already performed within the previous 12 months." (PMID 29122851, 2018). "It is important to note that albumin and transferrin levels do not always reflect actual protein status, since they are affected by other conditions, including inflammation, liver disease, and nephrotic syndrome, which were not investigated in this study." (PMID 29324643, 2018). "The strongest predictors among all liver disease etiologies were: older age, male sex, Hispanic ethnicity, high serum AFP level, alkaline phosphatase level and AST/√ALT ratio, and low platelet count and serum albumin level." (PMID 30260995, 2018). "In univariable analyses, the most important predictors of HCC among all liver disease etiologies were older age, male sex, Hispanic ethnicity, high serum AFP level, alkaline phosphatase level and AST/√ALT ratio, and low platelet count and serum albumin level." (PMID 30260995, 2018). "The patients who were included in our study were cirrhotic patients with ascites (as evidence of portal hypertension) whose hyponatremia did not improve with albumin challenge (25 g IV q6 h) for 48 h." (PMID 28352627, 2017). "The joined list consists of 15 optimal attributes: age, height, prothrombin time, spleen thickness, pararenal shunt, portal vein median velocity, haptic vein damping index, liver stiffness, liver disease, AST, albumin, spleen length, umbilical shunt, splenic vein width, gender, and spleen stiffness." (PMID 29158886, 2017).
liver disease (continued). "Thirdly, when describing the relationship between serum albumin and postoperative fever, we failed to exclude interference factors such as nutrition disorders or liver diseases in our study." (PMID 28261611, 2017). "We think that its reliance on age and albumin as factors in the score contributed to the poor performance in elderly patients with no advanced liver disease like ours." (PMID 27648468, 2016). "In both studies, lower concentrations of vitamin D were associated with most but not all markers of underlying liver disease, such as higher serum AST/ALT, higher measures of alkaline phosphatase and lower albumin." (PMID 27832143, 2016). "Univariable analysis showed most important criteria associated with lack of SVR, i.e. current or history of decompensated liver disease (RR 0.66), platelet count (RR 0.58), albumin (RR 0.49), bilirubin (RR 0.58) and neutrophil count (RR 0.55)." (PMID 27598789, 2016). "We demonstrated reduced hepatic synthetic function (albumin and prothrombin) during liver disease progression among studied groups, but neither was correlated with miRNAs." (PMID 26352740, 2015). "Neither survival nor hepatorenal syndrome reversal was significantly affected by vasoconstrictor dose or type, treatment duration, age, baseline serum creatinine, bilirubin or albumin, baseline mean arterial pressure, or study design, size or time period." (PMID 26606982, 2015). "Inclusion criteria were: age ≥ 65 years, primary unilateral THA, pre-operative serum albumin > 30 g/L, and no history of liver disease, nephrotic syndrome or malignancy that could affect albumin metabolism." (PMID 41630248, 2026). "Although serum albumin levels can also decrease in many other clinical situations (septic states, nephrotic syndrome, systemic inflammatory disorders, etc.), it can still be considered—but not always—a marker of liver disease severity." (PMID 40647574, 2025). "Changes in albumin levels are not specific for liver disease, but are also affected by a variety of pathological conditions, including undernutrition and protein‐leakage disease, and albumin levels have been shown to be a significant predictor of adverse outcomes in patients with HF." (PMID 39101582, 2024). "In the subgroup analysis stratified by sex, race/ethnicity, and liver disease, the negative correlation of ALB with ALP remained for most groups, except in blacks (β = −1.755, 95%CI: [−3.848, 0.338], P = .103) and patients with gout (β = −0.676, 95%CI: [−2.061, 0.709], P = .340)." (PMID 38552093, 2024). "Hepatorenal syndrome—a diagnosis of exclusion—may be suspected if the albumin volume challenge fails to improve renal function." (PMID 38966126, 2024). "In the subgroup analysis stratified by sex, race/ethnicity, liver disease, arthritis, and gout, the negative correlation of ALB with bone ALP remained, except for black individuals (β = −1.755, 95%CI: [−3.848, 0.338], P = .103) and patients with gout (β = −0.676, 95%CI: [−2.061, 0.709], P = .340)." (PMID 38552093, 2024). "AUDC + ve group showed more evidence of liver disease, in the form of higher concentrations of serum total and direct bilirubin, Alkaline Phosphatase (ALP), Gamma- Glutamyl Transferase (GGT) and lower concentrations of total protein, albumin, and haemoglobin levels, when compared to AUDC-ve group." (PMID 38028602, 2023). "Moreover, 13 studies (including all 10 studies dealing with the Ischemia-modified Albumin/Albumin ratio) only mentioned factors that were neither related to inflammation nor nutrition (e.g., liver disorders)." (PMID 37834777, 2023). "Furthermore, approximately one-half of the ATTIRE trial’s standard treatment arm received albumin during hospitalization for complications such as SBP and hepatorenal syndrome because withholding albumin in such cases would be contrary to management guidelines." (PMID 39132612, 2023).
liver disease (continued). "Similarly, we did not detect a correlation between eSMM and the markers of liver disease severity captured in this study (albumin, INR, AST, platelet count, and APRI)." (PMID 37902507, 2023). "The role of impairments in albumin function in the pathogenesis of liver disease is currently uncertain, and it is not yet clear whether these impairments are a cause or a result of the disease." (PMID 38137829, 2023). "However, in keeping with the EASL/American Association for the Study of Liver Diseases (AASLD) criteria, none of the three scores including MELD, Child–Pugh, and albumin-bilirubin (ALBI) were considerably related to the in-hospital mortality." (PMID 37469934, 2023). "The serum albumin is not a standout marker of liver disease in marine mammals." (PMID 37443929, 2023). "According to the Baveno VII consortium, there is an indication for short-term albumin administration in patients with SBP, acute kidney injury (AKI), large-volume paracentesis (>5 L), and, in combination with terlipressin, in the treatment of hepatorenal syndrome (HRS)." (PMID 37511665, 2023). "For patients with PPH and without liver disease, ALB was the main predictor, which may be a better surrogate for patient frailty and overall nutritional status and stage of RV dysfunction." (PMID 35722097, 2022). "In addition, for AST, a higher incidence rate of 90-day mortality was found in the 4th quartile in the total PPH group but not PPH without liver disease (ALB: p = 0.025; AST: p = 0.031)." (PMID 35722097, 2022). "Abnormal ALB independently served as a risk variable for hospital mortality and 90-day mortality but not for 4-year mortality; however, it was significantly associated with 90-day and 4-year survival curves in both total PPH and PPH without liver disorders." (PMID 35722097, 2022). "ALB independently served as a risk variable for hospital mortality and 90-day mortality and was significantly associated with 90-day and 4-year survival rates in both total PPH and PPH without liver disease." (PMID 35722097, 2022). "The results of TRSF revealed that some covariates are associated with the survival of patients with liver transplants and that these covariates include sex, oedema, spiders, albumin and triglycerides, while others do not influence the survival of patients with liver disease." (PMID 36818901, 2022). "Our data showed that abnormal ALB, AST, ALT, and total bilirubin were associated with the length of hospital stay and ICU stay, hospital mortality, and 90-day and 4-year mortality in cardiac surgery patients without liver disease." (PMID 34790710, 2021). "However, decreased ALB levels often occur in end-stage liver diseases, such as hepatic failure, rather than short-term experimental liver injury because of its very long half-life." (PMID 34421606, 2021). "Abnormalities in liver enzymes are reported in similar frequencies despite the presence of pre-existing liver disease, and unexplained elevation of ALT/AST, an increase of bilirubin, and reduced albumin levels in a clinically suspect patient may indicate COVID-19 infection." (PMID 34777871, 2021). "There are probably other confounding variables that affect albumin level and were not accounted for and may have altered the results such as chronic inflammatory conditions and liver disease." (PMID 31936687, 2020). "Interestingly, there was a marginally positive correlation between serum zinc and albumin levels in subjects with but not in those without liver diseases (r = 0.4028, P = 0.0631 and r = 0.1360, P = 0.5567, respectively)." (PMID 31392541, 2020). "However, antibodies with specificity for albumin were also found in patients with nonviral liver disease as published by several other groups." (PMID 30930689, 2019). "However, overinterpretation of the measured concentrations of albumin as a marker of the severity of liver disease is not always merited." (PMID 29122851, 2018).
liver disease (continued). "Moreover, those ASGP-R imaging agents using albumin as backbone have long circulation time in blood, which is not to the advantage of imaging in liver disease." (PMID 27150943, 2016). "Furthermore, the inclusion of only Child A HCC patients might also explain why other parameters affected by liver disease, such as ICG-clearance or platelet counts and albumin were unable to predict postoperative LD." (PMID 25611592, 2015). "Although a number of biomarkers including albumin, platelets, hyaluronic acid and AST have been evaluated, there is currently no single marker which successfully predicts significant fibrosis in HBV-related liver disease, and multiple biomarkers are needed to complement clinical data." (PMID 25128299, 2014). "Although it was not possible to perform specific investigations in this patient, the history of massive edema, lowered plasma albumin level and the absence of renal and liver disease support that our patient experienced a protein-losing enteropathy in association with facial cellulitis and ChAc." (PMID 25332750, 2014). "In addition, some variables that may influence inflammation and albumin levels, such as liver diseases, dietary intake, and medication use, were not controlled." (PMID 40357031, 2025). "The reclassification trends in our study show that MELD 3.0, particularly the version without albumin, more frequently increases MELD scores for women with advanced liver disease, whereas men were more commonly upshifted from lower MELD categories (MELD < 20)." (PMID 40996603, 2025). "The patient had no prior history of liver disease, and her synthetic liver function remained intact, with normal international normalized ratio (INR) and serum albumin levels." (PMID 40995286, 2025). "In the combined therapy group, the albumin–bilirubin (ALBI) score, the frequencies of radiological (non-clinical) ascites, and portal hypertension were significantly higher." (PMID 36937990, 2023). "Platelet count, serum albumin, CTP, and MELD scores were found to be predictors of survival in portal hypertensive patients (p < 0.05); the Glasgow Blatchford score did not affect the clinical outcome in these patients." (PMID 36431131, 2022). "For ALB, in both total PPH and PPH without liver disease groups, the group exhibiting a lesser value compared to the normal had a greater risk of 90-day mortality." (PMID 35722097, 2022). "The serum albumin–ascites gradient (SAAG) and albumin concentration in ascitic fluid (AFA) were measured to establish their sensitivity and specificity for determining the presence or absence of portal hypertension (PH)." (PMID 33102752, 2020). "Age, albumin (ALB) and prothrombin time (PT) were not significantly different in patients with various liver diseases (P > 0.05)." (PMID 32701483, 2020). "There was no data on AST, viral hepatitis, and history of liver disease, which would need to be used in the adjustment for the potential role of the liver function tests (ALT, GGT, ALP, Albumin and bilirubin) in the Cox model." (PMID 33261565, 2020). "Among the parameters examined in the present study, patients with PoPH exhibited lower levels of albumin and Hb and increased Child–Pugh and MELD scores compared with patients without PoPH, reflecting more serious liver disease in patients with PoPH." (PMID 30319722, 2018). "Postoperative outcomes according to the Albumin-Indocyanine Green Evaluation (ALICE) grade and presence/absence of portal hypertension in the Child-Pugh A patients of the entire Japanese cohort." (PMID 27434062, 2016). "Multivariate logistic regression analysis revealed that patients with elevated ALT who had liver disease had significantly higher GGT values and lower ALB and PLT counts than patients without liver disease." (PMID 24260428, 2013).
liver disease (continued). "Finally, standard LFTs predominantly reflect liver injury (e.g., AST, ALT), synthetic capacity (e.g., INR, albumin), or cholestasis (e.g., ALP, gamma-glutamyl transferase (GGT)), but do not directly assess fibrosis or portal hypertension." (PMID 41446460, 2025). "In our study, we found that decompensated cirrhotic infected with SARS-CoV-2 had decreased lymphocytes and RBC count, lower hemoglobin, and ALB level, prolonged PT, and APTT as well as evaluated ALT, AST, and TBIL compared with COVID-19 patients without liver disease." (PMID 33870852, 2021). "Serum chemerin correlated with markers of hepatic function (total bilirubin, albumin, INR) and inversely correlated with indicators of portal hypertension (platelet count, gastrointestinal bleeding) but not with extrahepatic organ failure and systemic inflammation." (PMID 29915268, 2018). "In patients without liver disease, the synthetic function of the liver is relatively normal, and the elevated level of ALP can better reflect the activation of systemic inflammatory response, while the level of ALB can better reflect the overall nutritional and metabolic status of the body." (PMID 40371078, 2025). "Some of the variables that are traditionally used in predicting severity of liver disease did not have any significant contributions to the prediction of hospital mortality in patients with acute decompensation of ALC, including platelet count, neutrophile count, serum albumin and AST level." (PMID 39458158, 2024). "Although hyperbilirubinemia alone is not an exclusive symptom of liver diseases, its interpretation, together with other parameters, such as CD4+ levels, albumin levels, platelets, and elevated liver enzymes, could help healthcare professionals identify HIV patients at risk for liver complications." (PMID 38787212, 2024). "In addition, for AST, a higher incidence rate of hospital mortality was found in patients belonging to the group with a higher value than normal only in the total PPH group (for total patients with PPH, ALB: p = 0.001; AST: p = 0.022; for patients with PPH and without liver disease, ALB: p = 0.001)." (PMID 35722097, 2022). "While albumin and platelet levels did not significantly differ between groups, there were numerical differences, indicating that in part the group who developed HCC may have had more advanced liver disease." (PMID 36138741, 2022).